CEACAM21 (CEA cell adhesion molecule 21)
Synonyms: R29124_1; FLJ13540
Tractability: Antibody: UniProt predicts a signal peptide or a membrane-spanning region.
Gene: Protein-coding gene on chromosome 19 (41,549,518 to 41,586,844, forward strand). Ensembl gene ENSG00000007129.
Subcellular location: Membrane
Gene Ontology:
Biological process: immune response; T cell activation
Cellular component: external side of plasma membrane; membrane
Genetic constraint (gnomAD): Loss-of-function variants: 38 observed, 34.85 expected, observed/expected ratio (o/e) 1.09, 90% interval 0.84 to 1.43. The upper end of that interval is the gene's LOEUF score, 1.43, which puts it in group 5 of 6, group 1 being the genes least tolerant of losing a copy. Missense variants: 385 observed, 378.7 expected, observed/expected ratio (o/e) 1.02, 90% interval 0.93 to 1.11. Synonymous variants: 156 observed, 147.93 expected, observed/expected ratio (o/e) 1.05, 90% interval 0.93 to 1.2.
Homologues: Orthologues: dog CEACAM1 (47% identical), mouse Ceacam9 (33% identical), rat Ceacam9 (33% identical), mouse Ceacam15 (31% identical), guinea pig Speradb (31% identical), rat Ceacam15 (30% identical), rat Ceacam15l1 (27% identical). Paralogues in human: CEACAM1 (48% identical), CEACAM5 (43% identical), CEACAM6 (42% identical), CEACAM3 (41% identical), CEACAM7 (40% identical), CEACAM8 (40% identical), CEACAM4 (37% identical), PSG2 (35% identical), PSG8 (35% identical), PSG4 (35% identical), PSG6 (35% identical), PSG9 (34% identical), and 12 more.
Diseases named in the same sentence as CEACAM21 in open-access papers:
CEACAM21 is named in the same sentence as 6 diseases in open-access papers, as found by Europe PMC text mining. Sharing a sentence is not in itself a finding about the gene and the disease. The quoted sentences say what the papers report.
prostate carcinoma (5 papers, 2019 to 2021). A carcinoma that arises from epithelial cells of the prostate gland. "CRISPR/Cas9-mediated introduction of single nucleotide mutation was used to directly demonstrate that the presence of allele G led to higher levels of PCAT19 and CEACAM21 transcripts; the genotype of rs11672691 was successfully converted from G/A to G/G or A/A in prostate cancer cell line 22Rv1." (PMID 34208629, 2021). "CRISPR/Cas9-mediated interference and activation assays have demonstrated that rs11672691 variant is involved in the regulation of its eQTL genes PCAT19 and CEACAM21 expression and affects the cells’ aggressive property in prostate cancers." (PMID 32523949, 2020). "The SNP, rs11672691, resides in an active enhancer element and the risk G allele increases the chromatin binding of HOXA2, which subsequently promotes the expression of PCAT19 and CEACAM21, which may contribute to the aggressive phenotype of prostate cancer." (PMID 31013831, 2019). "Recent studies have reported that prostate cancer risk-associated G allele of rs11672691 is associated with an increased expression of lincRNA PCAT19 and oncogene CEACAM21; SNV rs11672691 is located in an enhancer element and may alter the binding site of its oncogenic transcription factor HOXA2." (PMID 32523949, 2020).
prostate tumor (1 paper, 2023). "They analyzed the expression of two previously unknown PC genes, PCT19 and CEACAM21, and found that aggressive CRPC is associated with the G allele rs11672691, which is involved in regulation of PCT19 and CEACAM21 gene expression and affects the cellular properties of the prostate tumor." (PMID 37628978, 2023).
CEACAM21 also shares sentences with these, for which no sentence is quoted: COVID-19 (2 papers); cancer (1); serous ovarian cancer (1); tumor (1).